ITGB5 (integrin subunit beta 5)
Diseases named in the same sentence as ITGB5 in open-access papers (continued):
Sharing a sentence is not in itself a finding about the gene and the disease.
melanoma (3 papers, 2021 to 2025). A malignant, usually aggressive tumor composed of atypical, neoplastic melanocytes. "Reports concerning the role of ITGB5 in melanoma are scarce." (PMID 34660316, 2021). "Congruently, exploration of scRNA-seq data (via Single Cell Portal) revealed that elevated levels of ITGAV, ITGB3 and ITGB5 in myeloid cells are negative predictors of ICI therapy response in melanoma and renal cell carcinoma patients." (PMID 40281508, 2025).
non-small cell lung carcinoma (3 papers, 2011 to 2018). A group of at least three distinct histological types of lung cancer, including non-small cell squamous cell carcinoma, adenocarcinoma, and large cell carcinoma. "Itgb5 protein has been investigated as diagnostic biomarker in non-small cell lung cancer and is target of the inhibitor drug EMD121974, which is under clinical trial." (PMID 22078386, 2011). "We also see Steiner nodes such as CBL and ITGB5, which have been shown to be involved in several models of non-small cell lung cancers, like the H358 cells." (PMID 28759592, 2017).
ovarian carcinoma (3 papers, 2013 to 2024). A malignant neoplasm originating from the surface ovarian epithelium. "From the total of 34 ligand and receptor genes identified in these interactions, seven (COL1A1, ITGB5, COL1A2, FGFR2, FN1, IGF1, and IGF2) were consistently up-regulated and predicted worse overall survival in two additional cohorts (TCGA and GSE9891) of ovarian cancer patients." (PMID 36352420, 2022).
prostate carcinoma (3 papers, 2021 to 2022). A carcinoma that arises from epithelial cells of the prostate gland. "This suggests that ITGB5 is a potential proto-oncogene in the prostate cancer LNCap cell line, while TMP1 and TMEM176B are potential tumor suppressor genes." (PMID 34109215, 2021). "We designed different CRISPR transcriptional regulatory systems to silence ITGB5 in prostate cancer cells and activate TIMP1 and TMEM176B at the same time." (PMID 34109215, 2021). "In this study, we found that compared with prostate hyperplasia cells BPH, ITGB5 is significantly higher expressed in prostate cancer cells, and TMP1 and TMEM176B are significantly lower expressed." (PMID 34109215, 2021). "Although ITGB5, TIMP1, and TMEM176B are abnormally expressed in several cancers, their molecular biological mechanisms in prostate cancer cells are still to be investigated." (PMID 34109215, 2021). "Through a series of cellualr experiments, we found that inhibition of ITGB5 or activation of TIMP1 and TMEM176B suppress prostate cancer." (PMID 34109215, 2021). "In this study, we used CRISPR interference (CRISPRi) and CRISPR activation (CRISPRa) technologies to regulate the transcription of ITGB5, TIMP1, and TMEM176B in prostate cancer cells." (PMID 34109215, 2021). "In this work, we have used CRISPR interference (CRISPRi) and CRISPR activation (CRISPRa) technologies to study the biologocal functions of ITGB5, TIMP1, and TMEM176B in prostate cancer cells." (PMID 34109215, 2021). "We found that ITGB5 was significantly higher in prostate cancer compared with BPH cells, and that TMP1 and TMEM176B were significantly low expressed in prostate cancer." (PMID 34109215, 2021). "We compared the expression levels of eight integrin subunits (ITGA2, ITGA5, ITGAV, ITGB1, ITGB3, ITGB4, ITGB5, and ITGB6), HOXB13, HOXA11-AS, CCL2, CXCL12, and IBSP in prostate cancer tissues that had metastasized to bone, lymph nodes, lungs, liver, and other organs." (PMID 33514011, 2021). "Although these evidences suggest that ITGB5, TIMP1, and TMEM176B may work together to promote the invasion and metastasis of cancer cells, their molecular biological mechanisms in prostate cancer cells are still unclear and require further research." (PMID 34109215, 2021).
asthma (2 papers, 2013 to 2024). "An AHR GWAS among 994 asthma patients found that the most strongly associated SNPs, rs848788 (P-value 7.2E-07) and rs6731443 (P-value 2.5E-06), were in the ITGB5 and AGFG1 genes, respectively." (PMID 23984888, 2013). "We utilized data from 994 non-Hispanic white asthma patients to measure the association of single nucleotide polymorphisms (SNPs) with severity of AHR and found that the strongest associations were at variants in two genes: ArfGAP with FG repeats 1 (AGFG1) and integrin, beta 5 (ITGB5)." (PMID 23984888, 2013).
Brain atrophy (2 papers, 2023 to 2025). Partial or complete wasting (loss) of brain tissue that was once present. "The T al. result implies an association of ITGB5 with amyloid accumulation and brain atrophy, as it was associated with slower atrophy in the hippocampus, ventricle, and entorhinal cortex but faster atrophy in the parietal gray matter." (PMID 40106490, 2025).
cardiomyopathy (2 papers, 2016). A disease of the heart muscle or myocardium proper. "Some DEGs related to cytoskeleton organization (e.g. MTSS1, ACTN4 and CALD1), cardiomyopathy (e.g. ITGB5) and immune response (e.g. C1S and C1R), as well as some regulators (e.g. LEF1 and hsa-miR-33a) might play pivotal roles in the progression of DN." (PMID 27613243, 2016).
Cognitive impairment (2 papers, 2023 to 2025). Abnormal cognition is characterized by deficits in thinking, reasoning, or remembering. "In addition, they concluded that higher levels of ITGB5 may act as a marker of reduced dementia risk, as a higher expression level of ITGB5 is associated with reduced odds of cognitive impairment." (PMID 40106490, 2025).
colorectal cancer (2 papers, 2012 to 2014). A primary or metastatic malignant neoplasm that affects the colon or rectum. "The result of the remained patients showed that, except for ITGB5, the other three genes COL1A1, FN1and SPP1were up-regulated in six cancer samples, and the COL3A1 was up-regulated in four cancer samples, suggesting the ECM-pathway genes are usually up-regulated in colorectal cancer." (PMID 22905095, 2012).
coronary artery disease (2 papers, 2021 to 2022). "Itgb5 (Integrin Subunit Beta 5) has been identified to be in significant correlation with coronary artery disease and age-dependent organ fibrosis." (PMID 34130651, 2021). "ITGB5 was suggested as a biomarker for both nonprogressive and progressive kidney diseases, and was also one of the genes strongly associated with ischemic heart disease." (PMID 35347083, 2022).
diabetic cardiomyopathy (2 papers, 2016 to 2022). Diabetic cardiomyopathy is a disorder of the heart muscle in people with diabetes. "The members of integrin family, especially ITGAV and ITGB5, are potential receptors of irisin in osteocytes and fat cells, and simultaneous knockdown of ITGAV and ITGB5 also blocked FNDC5‐mediated protective effects against diabetic cardiomyopathy." (PMID 35166002, 2022).
keloid (2 papers, 2021 to 2023). An irregularly shaped, elevated mark on the skin caused by deposits of excessive amounts of collagen during wound healing. "Interestingly, we found that the POSTN-ITGAV;ITGB5 interactions between mesenchymal and other fibroblasts were significantly increased in keloid compared to normal scar." (PMID 34140509, 2021).
leukemia (2 papers, 2014 to 2018). A malignant (clonal) hematologic disorder, involving hematopoietic stem cells and characterized by the presence of primitive or atypical myeloid or lymphoid cells in the bone marrow and the blood. "Herein we show that in leukemia cells ERG overexpression promotes a mesenchymal-like gene expression signature that includes: CD24, CD44, ITGA10, ITGB5, ITGB3, ITGA2B and the morphogenic-associated genes, such as SHANK3, TYROBP." (PMID 24504051, 2014).
liver fibrosis (2 papers, 2022 to 2024). "Itgb5, which was up-regulated by over 1000-fold in all FS groups, encodes integrin beta 5, a protein involved liver fibrosis." (PMID 36235565, 2022). "Importantly, PI3K-AKT and focal adhesion-related proteins, such as PDGFRβ, PIKR3R1, ITGB5, COL1A1, COL6A1, COL6A3, and LAMA5, are mainly associated with liver fibrosis." (PMID 38469403, 2024).
migraine (2 papers, 2020 to 2024). "TWAS genes with independent effects shared by subtypes of migraine and BP were consistent with findings for overall migraine at ITGB5, while identifying additional associations at HMOX2 for MA and BP, and HVCN1 and MANBA for MO and BP." (PMID 32632093, 2020). "Lead SNP rs6438857 (at chr3q21.2, PCPASSOC = 2.64 × 10−22, 1.77 × 10−23, 2.55 × 10−14 for DBP, SBP, and PP, respectively based on SHet statistic) implicating ITGB5 was the only locus that was shared between migraine and all the three BP measurements." (PMID 32632093, 2020).
psoriasis (2 papers, 2022 to 2024). An autoimmune condition characterized by red, well-delineated plaques with silvery scales that are usually on the extensor surfaces and scalp. "In particular, ITGB5 was significantly increased in the serum of patients with psoriatic arthritis, a distinct inflammatory arthritis occurring in 30% of psoriasis patients." (PMID 35347083, 2022).
psoriatic arthritis (2 papers, 2022). Joint inflammation associated with psoriasis. "Consistently, ITGB5 was also found to be upregulated in chronic kidney disease and psoriatic arthritis." (PMID 35347083, 2022). "Based on the results of the validation analysis, the authors proposed integrin β5/ITGB5 as a candidate biomarker of psoriatic arthritis." (PMID 35327421, 2022). "Because Cretu’s study had two significant limitations: the researchers pooled samples (n = 5) before analyzing them by LC-MS/MS, and only two proteins, namely ITGB5 and POSTN, were validated by ELISA, other attempts to identify the biomarkers of psoriatic arthritis followed." (PMID 35327421, 2022).
acute myeloid leukemia (1 paper, 2021). Acute myeloid leukemia (AML) is a group of neoplasms arising from precursor cells committed to the myeloid cell-line differentiation. "The decreased expression of CEACAM1 and EPHA2 was found to be associated with several cancers, but ITGB5 reduction in expression was associated with acute myeloid leukemia (LAML) only." (PMID 34908921, 2021).
adenovirus infection (1 paper, 2012). "Moreover, it has been reported that the polymorphisms of ITGB5 is the host factor which might affect adenovirus infection and decrease lung function in human." (PMID 22457712, 2012).
airway hyperresponsiveness (1 paper, 2019). "In a porcine model, the ITGB5 gene was reported to be a significant adhesion molecule of mucosal epithelial signaling in the response to Escherichia coli, while, in humans, ITGB5 variants were associated with airway hyperresponsiveness." (PMID 31569353, 2019).
amyotrophic lateral sclerosis (1 paper, 2025). Amyotrophic lateral sclerosis (ALS) is a neurodegenerative disease characterized by progressive muscular paralysis reflecting degeneration of motor neurons in the primary motor cortex, corticospinal tracts, brainstem and spinal cord. "Interestingly, overexpression of ITGB5 was found in amyotrophic lateral sclerosis, which is a progressive neurodegenerative disease, consistent with the progressive pattern of NPC." (PMID 40106490, 2025).
arrhythmogenic right ventricular cardiomyopathy (1 paper, 2016). "Besides, some other ones were correlated with arrhythmogenic right ventricular cardiomyopathy (e.g. ACTN4, CTNNA1 and ITGB5), as well as complement and coagulation cascades (e.g. C1R and C1S)." (PMID 27613243, 2016).
astrocytomas (1 paper, 2025). "ITGAV and ITGB5 expression was also elevated in astrocytomas." (PMID 40281508, 2025).
breast tumor (1 paper, 2017). "While, another study on ITGB5 showed its crucial role in the tumorigenesis of breast tumor cells." (PMID 28587194, 2017).
Cerebral ischemia (1 paper, 2023). Restriction of arterial blood supply to the brain associated with insufficient oxygenation to support the metabolic requirements of the tissue. "Compared to WT mice, Lrg1−/− mice exhibited increased protein levels of cell adhesion-related molecules, including Cldn11, Anxa2, Pcdh9, and Itgb5, in endothelial cells after cerebral ischemia‒reperfusion injury." (PMID 38037097, 2023).
COVID-19 (1 paper, 2024). A disease caused by infection with severe acute respiratory syndrome coronavirus 2. "Integrin-related genes, including ITGA1, ITGB3, ITGB5, and ITGB8, have been less investigated in patients with COVID-19 myocarditis and may be potential prognostic biomarkers." (PMID 39026189, 2024).
depression (1 paper, 2025). "ITGB5 plays a role in neuroinflammation by modulating the activation of glial cells, such as microglia, which are implicated in both AD and depression." (PMID 40074694, 2025). "Therefore, the molecular mechanisms underlying ITGB5's dysregulation in AD with depression is worthy of further investigation, which could provide valuable insights into new therapeutic targets for complex neurodegenerative and psychiatric disorders." (PMID 40074694, 2025). "To date, there is limited direct evidence linking ITGB5 to AD with depression." (PMID 40074694, 2025). "The AUC of the nomogram was 0.841, indicating that ITGB5 and SPCS1 are good biomarkers in diagnosing AD with depression." (PMID 40074694, 2025). "Therefore, ITGB5 may be a promising therapeutic target for AD with depression." (PMID 40074694, 2025). "The most notable finding is that we identified two predictive genes (ITGB5 and SPCS1) and formed a nomogram for diagnosing AD with depression." (PMID 40074694, 2025). "In addition, ITGB5 showed a strong correlation with several immune cell types, particularly Natural Killer T cells (r = 0.7455, p < 0.01), suggesting ITGB5 might play a role in the migration and activation of immune cells, thereby influencing the immune response in AD with depression patients." (PMID 40074694, 2025). "Furthermore, the nomogram indicated that ITGB5 and SPCS1 are good biomarkers in diagnosing AD with depression." (PMID 40074694, 2025). "Therefore, ITGB5 and SPCS1 were used as predictive biomarkers of AD with depression." (PMID 40074694, 2025).
lymph node metastasis (1 paper, 2022). "ITGB5 expression was related with tumor size, lymph node metastasis, and clinical stage significantly (p < 0.05)." (PMID 36249018, 2022).
metastatic prostate carcinoma (1 paper, 2021). A carcinoma that arises from the prostate gland and has spread to other anatomic sites. "Among the eight integrin subunits analyzed, ITGA5, ITGAV, ITGB1, ITGB3, ITGB4, and ITGB5 were upregulated in the bone compared with the other organs, suggesting that some integrins may confer osteotropic properties on metastatic prostate cancer." (PMID 33514011, 2021).
Myocardial fibrosis (1 paper, 2018). "We inferred that EXD may mitigate myocardial fibrosis in OVX rats by decreasing the expression of Itgb5." (PMID 30176849, 2018).
myocardial infarction (1 paper, 2023). Gross necrosis of the myocardium, as a result of interruption of the blood supply to the area, as in coronary thrombosis. "Itgb2 expression showed an early peak, 3 days after myocardial infarction, whereas Itgb5 mRNA levels progressively increased after 3 and 7 days." (PMID 37985764, 2023).
Obesity (1 paper, 2021). Accumulation of substantial excess body fat. "It was found that the mRNA expression levels of STAT3, CORO1C, SERPINH1, MVP and ITGB5 were significantly increased in the obesity compared with the control group." (PMID 34248836, 2021).
oral cancer (1 paper, 2024). "The upregulation of ENAH through a PI3K/AKT/β-catenin signaling cascade enhances oral cancer cell migration and growth via the ITGB5/Src axis." (PMID 39511483, 2024).
osteosarcoma (1 paper, 2021). A usually aggressive malignant bone-forming mesenchymal neoplasm, predominantly affecting adolescents and young adults. "In addition, somatic mutations in COL6A3 and ITGB5 have been documented for osteosarcoma samples in COSMIC." (PMID 34570764, 2021). "In the case of module 3 genes associated with osteosarcoma, eight are found in COSMIC (LUM, COL6A3, TNC, CALU, COL16A1, OMD, ITGB5, and DPSYL3), and two (CDH11 and OMD) are oncogenes found in OncoKB." (PMID 34570764, 2021). "The fact that COL6A3, COL5A2, TNC, and ITGB5 which are highly activated here and part of the focal adhesion-PI3K-Akt signaling axis implies that they are central to osteosarcoma and not simply tissue specific activation." (PMID 34570764, 2021).
prostate intraepithelial neoplasia (1 paper, 2013). A neoplastic proliferation of the epithelial cells that line the acini and the ducts of the prostate gland. "It has also been shown that ITGB5 (encoding integrin subunit β5) is overexpressed in prostate intraepithelial neoplasia (PIN) tissue, suggesting its potential role in the early-stage prostate tumorigenesis." (PMID 23365759, 2013).
rheumatoid arthritis (1 paper, 2015). A chronic, systemic autoimmune disorder characterized by inflammation in the synovial membranes and articular surfaces. "Apart from acting as a POSTN ligand (along with ITGA5), ITGB5 has also been implicated in rheumatoid arthritis, where it serves as a ligand for Cyr61." (PMID 25678896, 2015).
scleroderma (1 paper, 2023). Scleroderma is a rare autoimmune connective tissue disorder characterized by abnormal hardening of the skin and, sometimes, other organs. "ADSCs also expressed fibronectin type III domain-containing protein 5 (FNDC5), which interacted with ITGB5 and additionally with ITGAV in scleroderma on various subclusters." (PMID 37443817, 2023). "ADSCs also expressed FNDC5, a fibronectin, which interacted with ITGB5 and additionally with ITGAV in scleroderma." (PMID 37443817, 2023).
skin cancer (1 paper, 2023). "Specifically, the ligand SERPINE1, which binds to the receptor ITGB5, has been found to promote tumor growth and angiogenesis in several types of cancer, including skin cancer." (PMID 37510272, 2023).
villous adenocarcinoma (1 paper, 2014). An adenocarcinoma characterized by the presence of a villous architectural pattern. "The overexpression of the matrix extracellular genes ITGA-3 and ITGB-5 is associated with advanced stage tumors, and the genes MMP-2 and MMP-9 are overexpressed in mucinous and villous adenocarcinoma type tumors, respectively." (PMID 24737953, 2014).